MALAT1 (metastasis associated lung adenocarcinoma transcript 1)
Diseases named in the same sentence as MALAT1 in open-access papers (continued):
Sharing a sentence is not in itself a finding about the gene and the disease.
lung cancer (continued). "MALAT1, a prognostic marker for lung cancer metastasis, is an lncRNA that was first found in non-small cell lung cancer." (PMID 27564100, 2016). "Surprisingly, LC patients had lower expression of MALAT1 than healthy subjects in whole blood which was contrary to the high expression of MALAT1 in lung cancer tissues." (PMID 27143813, 2016). "The potential of lncRNAs as diagnostic biomarkers was also confirmed by several meta-analyses with MALAT1 and the human urothelial carcinoma associated 1 (UCA1) as most promising candidates in lung cancer patient." (PMID 28035947, 2016). "MALAT1 is up-regulated in human lung cancers, breast cancers, pancreatic cancers, colon cancers, prostate cancers, and endometrial stromal sarcomas." (PMID 26735578, 2016). "Some researcher discovered that upregulation of MALAT1 was mediated by the transcription factor Sp1 in A549 lung cancer cells." (PMID 27777857, 2016). "For lung cancer, various lung cancer-specific lncRNAs have been identified, such as MALAT1, TARID, and LUADT1." (PMID 27154193, 2016). "Injection of ASO into subcutaneous tumors of nude mice effectively inhibits MALAT1 in vivo and blocks metastasis of lung cancer cells." (PMID 26448935, 2015). "In a MALAT1 knockout model of human lung cancer cells it was shown that MALAT1 regulates metastatic signature of genes." (PMID 25954300, 2015). "A notorious example of such an oncogenic lncRNA is metastasis-associated lung adenocarcinoma transcript 1 (MALAT1) which, as indicated by its name, was initially found over-expressed in lung cancer metastases." (PMID 24346158, 2014). "Another highly abundant lincRNA MALAT1 (also known as NEAT2) is originally identified as a marker for lung cancer metastasis; its expression is strongly regulated in many tumor entities including lung adenocarcinoma and hepatocellular carcinoma." (PMID 25075616, 2014). "Recent studies show that knocking-down MALAT1 expression impairs lung adenocarcinoma cell mobility and metastasis, suggesting the important role of MALAT1 in lung cancer metastasis." (PMID 24742640, 2014). "MALAT1, a biomarker for lung cancer metastasis, can govern hallmarks of lung cancer metastasis through regulation of metastasis-related genes expression." (PMID 24810364, 2014). "MALAT1, also known as NEAT2 (nuclear-enriched abundant transcript 2), is a highly conserved nuclear lncRNA and a predictive marker for metastasis development in lung cancer." (PMID 24655544, 2014). "The long noncoding RNA MALAT1 induces lung cancer cell migration and plays a pivotal role in lung cancer metastasis." (PMID 24742640, 2014). "In a xenograft mouse model, the MALAT1-depleted lung cancer cells showed reduced tumor formation compared to the cells with the intact MALAT1." (PMID 24013378, 2013). "In lung cancer cells, downregulation of MALAT1 by siRNA decreases cell motility and downregulates motility-related genes, which suggests that MALAT1 promotes lung cancer metastasis." (PMID 23843741, 2013). "MALAT1 was first identified as a well-conserved, prognosis-related RNA in lung cancer, where its expression varied inversely with metastasis-free survival." (PMID 24305655, 2013). "The zinc finger nuclease-mediated knockout of MALAT1 led to a marked increase in apoptosis sensitivity in A549 lung cancer cells following incubation with staurosporine and cisplatin." (PMID 23717670, 2013). "A MALAT1 knockout model in lung cancer cell lines has shown a direct relationship between MALAT1 and increased metastasis." (PMID 24305655, 2013). "MALAT1 is overexpressed not only in lung cancer, but also in breast, pancreas, colon, prostate, and liver cancers, implying key roles in cancer progression." (PMID 23109937, 2012). "Our group suggested that MALAT1 promotes lung cancer cell motility, which is important for metastasis, through regulation of motility-related genes such as CTHRC1, CCT4, HMMR, and ROD1, transcriptionally and/or post-transcriptionally." (PMID 23109937, 2012).
lung cancer (continued). "MALAT-1 (metastasis in lung adenocarcinoma transcript 1), a recently identified noncoding RNA, has been shown to be activated in early-stage lung cancer." (PMID 17880733, 2007). "MALAT-1 and colon cancer-associated transcript 2 (CCAT2) genetic polymorphisms could predict the risk of lung cancer and the response to platinum-based chemotherapy." (PMID 39912974, 2025). "LncRNA MALAT1 is a key regulator in lung cancer pathogenesis and progression." (PMID 41373437, 2025). "Initially, MALAT1 was identified as a significant predictor of lung cancer." (PMID 40534842, 2025). "Additionally, we validated the imaging efficacy of Cy5.5-labeled MALAT1-ASO probes using lung cancer and skin squamous cell carcinoma-related cell lines in both in vitro and in vivo experiments." (PMID 40597438, 2025). "Therefore, MALAT-1 silencing prevents the migration and metastasis of highly invasive subline of lung cancer cells to the brain by triggering the EMT." (PMID 39912974, 2025). "Additionally, MALAT1 is overexpressed in several aggressive solid tumors, including Breast, esophageal, and lung cancer." (PMID 41303378, 2025). "MALAT1 RNA levels are altered by perturbation of TDP-43 expression in lung cancer cells." (PMID 39837396, 2025). "AA lung cancer patients show elevated MALAT1 and PVT1 levels compared to cancer-free smokers." (PMID 38791954, 2024). "Furthermore, five lung cancer cell lines including A549, H513, H1373, and H1385, and H520 exhibited higher levels of MALAT1 and MCP-1 compared to H460 and Beas-2B cells." (PMID 38791954, 2024). "MALAT1 was originally described as a prognostic marker of lung cancer metastasis." (PMID 38696425, 2024). "Therefore, dysregulated MALAT1 contributes to lung cancer disparities in AAs by modulating the tumor immune microenvironment through its interaction with miR-206, thereby presenting novel diagnostic and therapeutic targets." (PMID 38791954, 2024). "MALAT1 was initially found to be significantly elevated in metastatic lung cancer cells, and studies have shown that it plays an important role in the angiogenic capacity, invasion, and apoptosis of tumor cells, which is a potential biomarker for tumor prediction and treatment." (PMID 39199376, 2024). "Considering that supernatants may resemble plasma in vivo, this finding reflects our above observations in plasma samples from AA lung cancer patients, who also demonstrated increased MALAT1 levels in AA patients diagnosed with lung cancer." (PMID 38791954, 2024). "Recognizing how MALAT-1 and MDSCs interact in lung cancer might provide useful information about possible therapeutic targets for controlling the immunosuppressive TME and enhancing the effectiveness of lung cancer therapies." (PMID 38511067, 2024). "Since its discovery, MALAT1 has contributed significantly to the progression, metastasis, drug resistance, and treatment of the cancer, as well as its clinical importance in predicting the tumor metastasis of early stage, particularly lung cancer." (PMID 38517388, 2024). "To explore whether MALAT1 contributes to immune responses in lung cancer among AAs, we evaluated cytokines in the same plasma sets and compared these with the results for lncRNAs." (PMID 38791954, 2024). "The results imply that focusing on the MALAT-1/miR-200a axis may be a potential therapeutic approach for the management of lung cancer." (PMID 38511067, 2024). "However, only a small number of researches have looked into the connection between MALAT1 SNPs and lung cancer." (PMID 38517388, 2024). "The research shows that MALAT-1 promotes ZEB1 expression in lung cancer cells." (PMID 38511067, 2024). "Nevertheless, previous studies have shown that MALAT1 functions as an oncogene in cancer; however, our data suggest that MALAT1 may have a tumor suppressor function in lung cancer cells which is consistent with previous result." (PMID 38517388, 2024).
lung cancer (continued). "Like other lncRNAs such as HOTAIR in breast cancer and MALAT1 in lung cancer, ST8SIA6-AS1 could interact with chromatin-modifying proteins to influence gene expression epigenetically." (PMID 39211393, 2024). "For example, the lncRNA MALAT1 has been investigated as a lung cancer prognostic marker." (PMID 39325172, 2024). "Moreover, MALAT1 has been shown to negatively regulate myeloid‐derived suppressor cells (MDSCs) in lung cancer patients." (PMID 37901797, 2023). "For example, the metastasis-associated lung adenocarcinoma transcript 1 (MALAT1) lncRNA was first identified as having a potential role in cancer during a comparative screening of non–small-cell lung cancer patients with and without metastatic tumors." (PMID 37384249, 2023). "In summary, MALAT1 promotes metastasis in lung cancer, but may show opposite functions in different types of cancer depending on cellular context." (PMID 37370745, 2023). "Although not restricted to lung cancers, overexpression of MALAT1 has been associated with metastasis in several different types of cancer, though a smaller number of studies have reported that the lncRNA has a tumour suppressor role in some cancers." (PMID 35880706, 2023). "MALAT1 has been implicated in several aspects of lung homeostasis and dysregulation of MALAT1 is involved in the development and progression of different lung diseases, such as asthma, COPD, and lung cancer." (PMID 37250901, 2023). "MALAT1 has been shown to be aberrantly expressed and have prognostic and therapeutic significance in different cancers, including pancreatic cancer, lung cancer, breast cancer, colorectal cancer, gastric cancer, nasopharyngeal carcinoma, hepatocellular carcinoma, osteosarcoma." (PMID 37250901, 2023). "For example, HOTAIRM1 and MALAT1 are down-regulated in MDSCs from lung cancer patients." (PMID 36817434, 2023). "Similarly, overexpression of MALAT1 in cisplatin-sensitive A549 lung cancer cells increased tumor volume as compared to empty vector control." (PMID 37370745, 2023). "Most of the previous studies on MALAT1 were mainly on lung cancer and other tumors." (PMID 37873058, 2023). "However, MALAT1 was not only highly expressed in lung cancer but participated in the progression and expansion of hepatocellular carcinoma, endometrial stromal sarcoma, cervical, breast cancer, osteosarcoma, colorectal cancer and others." (PMID 36817434, 2023). "The subcutaneous administration of ASOs targeting MALAT1 effectively inhibited human lung cancer cell proliferation in a mouse xenograft model as well as in A549 lung cancer cells, which showed a great reduction in the MALAT1 expression level and decreased the migration ability in vitro." (PMID 37686376, 2023). "MALAT1 (metastasis associated lung adenocarcinoma transcript 1) was first identified in a study to find differences in gene expression between tumours of non‐small cell lung cancer that metastasised and those that did not." (PMID 35880706, 2023). "The positive effects were confirmed later by Gong and colleagues, who constructed a MALAT1-specific ASO that reduced the MALAT1 expression levels, decreased the migration ability in lung cancer cells, and significantly reduced the metastatic tumor nodule formation in vivo." (PMID 36012617, 2022). "Recent research results revealed that Malat1 is related to the metastasis of lung cancer cells." (PMID 35309141, 2022). "Blood MALAT1 levels are lower in patients with lung cancer than in healthy controls." (PMID 36419933, 2022). "In addition, the expression of the baseline MALAT1 in the pleural effusion of patients with lung cancer-MPE is negatively correlated with the efficacy of chemotherapy." (PMID 35651679, 2022). "MALAT1 affects lung cancer cell proliferation and metastasis through a dual pathway." (PMID 36419933, 2022).
lung cancer (continued). "LncRNA MALAT1 is differentially expressed in a variety of tumors, such as lung cancer, breast cancer, gastric cancer, prostate cancer and pancreatic cancer, and can promote tumor progression and play an important role in the regulation of cancer-related pathways." (PMID 35819532, 2022). "Indeed, administration of MALAT1 targeting ASOs reduced metastasis in both human lung cancer xenograft models and mouse mammary tumor models, while siRNA knockdown of MALAT1 reduced cell motility in vitro models." (PMID 36077530, 2022). "The potential role of MALAT1 in the treatment of lung cancer could be further evaluated by conducting experiments in mice using MALAT1 inhibitors followed by the simultaneous application of cancer impact factors in a control group." (PMID 36419933, 2022). "The aim was also extended to gain insight into whether simultaneous inhibition of STAT3 activation and FUT4 fucosylation via ALT and Brv-A have any impact on functional role of lncRNA MALAT1 in A549/T lung cancer cells." (PMID 35281907, 2022). "Particularly, MALAT1 was a predictive marker for metastasis development in lung cancer." (PMID 35928715, 2022). "Many studies have shown that MALAT1 participates in regulating tumor cell migration, and it can regulate metastasis-related genes at the transcription level or post-transcription level to enhance the migration ability of lung cancer cells." (PMID 35311148, 2022). "The lncRNA MALAT1 has been widely studied, and accumulating evidence indicates that MALAT1 acts as an oncogene in the process of various cancers (e.g., prostate cancer, gastric cancer, and lung cancer)." (PMID 35110552, 2022). "MALAT1 competes with endogenous miRNAs, regulates the expression levels of downstream genes and controls the proliferation, invasion, metastasis and apoptosis of lung cancer cells through various signaling pathways such as PI3K/Akt and Wnt/β-catenin." (PMID 36419933, 2022). "Since the discovery of MALAT1, it had played an important role in the occurrence, development, metastasis, drug resistance and clinical treatment of the disease 16, 24-30, especially in lung cancer." (PMID 35928715, 2022). "After establishing the expected role of MALAT1, STAT3, and FUT4 in resistant and non-resistant lung cancer cells, we further studied the association of MALAT1 with STAT3 and FUT4 expression in A549/T cells." (PMID 35281907, 2022). "MALAT1 plays a regulatory role in various types of lung cancer." (PMID 36419933, 2022). "However, the oncogene lncRNA plasmacytoma variant translocation 1 (PVT1), XIST, and MALAT1 have all been demonstrated to promote autophagy through LC3 cleavage, which can enhance the chemoresistance of lung cancer cells." (PMID 33931980, 2021). "In the present research, we demonstrated that MALAT1 level was upregulated only in esophageal cancer, acute myeloid leukemia, and stomach adenocarcinoma, and widely low expressed in most kinds of cancers, including lung cancer etc., by GEPIA." (PMID 34308750, 2021). "For a long time, MALAT1 was considered to be a nuclear marker in certain cancer cell lines, especially cancers with aggressive metastatic tumors, and it has been shown to be involved in proliferation and invasion of lung cancer cells and cervical cancer cells." (PMID 34012919, 2021). "Loss-of-function studies of MALAT1 in mice have revealed that it is non-essential for normal tissue homeostasis during development, but depletion of MALAT1 in lung cancer cells leads to a significant decrease in cell motility." (PMID 33435206, 2021). "In addition to targeting the protein-coding mRNAs, ASO targeting lncRNA MALAT1 dramatically prevented lung cancer metastasis in a pulmonary metastatic mouse model, showing attractive potentials for developing ASO drugs targeting functional ncRNAs to treat PCa." (PMID 33869227, 2021).
lung cancer (continued). "For instance, many studies showed MALAT1 to be upregulated in lung tumor tissues compared with the normal ones, suggesting its usefulness as biomarker in different body fluids for early detection of lung cancer." (PMID 34199799, 2021). "Furthermore, FYN can inhibit the invasion of A549 lung cancer cells by downregulating Malat1 to inhibit the Wnt/β-catenin/EMT signaling axis." (PMID 34277435, 2021). "The inhibition of MALAT1 could revert this effect, and inhibition of the MALAT1 interaction with miR-101 modulates cisplatin and temozolomide resistance in lung cancer and glioblastoma, respectively." (PMID 33808190, 2021). "Further results showed that MALAT1 can be used as a predictive biomarker of lung cancer." (PMID 34670194, 2021). "Obviously, MALAT1 cannot be used as a single molecular marker to diagnose early stage lung cancer." (PMID 33931980, 2021). "Notably, siRNA-mediated MALAT1 downregulation has been found to delay tumor growth and decrease metastasis in lung cancer xenograft models, indicating its potential as a therapeutic target." (PMID 33407724, 2021). "MALAT1 is another lncRNA that was first reported in lung cancer." (PMID 34439239, 2021). "In terms of lncRNA, TDP-43 could also bind the 3′ UTR of MALAT1 to maintain its stability in lung cancer; the knock-down of TDP-43 significantly suppressed cell proliferation and migration by downregulating the MALAT1 level." (PMID 34778070, 2021). "Moreover, UBE2C and MALAT1 were indicated as targets of miR-491-5p and inhibition of miR-491-5p restored the MALAT1 knockdown-induced inhibition of the progression of lung carcinoma." (PMID 34257576, 2021). "The results indicated that the expression of MALAT1 was often augmented in lung carcinoma cells." (PMID 34257576, 2021). "Moreover, more and more evidence has shown that MALAT-1 has potential application value in the clinical diagnosis of lung carcinoma, which suggests that MALAT-1 can be used as one of the indicators for the early NSCLC diagnosis." (PMID 34858541, 2021). "It showed that MALAT-1 has the ability to promote the formation of lung carcinoma." (PMID 34858541, 2021). "Among the assessed lncRNAs was MALAT1, a well-recognized oncogenic lncRNA in lung cancer." (PMID 32514489, 2020). "Moreover, from this list, only H19, MALAT1, HOTAIR, and GAS5 were associated with exosomes and lung cancers in our PubMed search." (PMID 32438606, 2020). "MALAT1 was one of the first human lncRNAs identified in metastatic lung cancer cells." (PMID 33293956, 2020). "Inhibitors targeting MALAT1 significantly reduced lung cancer metastasis in a mouse model." (PMID 32819367, 2020). "The reduced expression of MALAT1 in the patients with lung cancer led to the increased proportions of MDSCs, indicating that MALAT1 could prevent the differentiation of tumor MDSCs." (PMID 33613512, 2020). "MALAT-1 is highly expressed and mediates poor progression in lung cancer." (PMID 31956359, 2020). "Reports indicate that miR-101-3p targets Pim-1 in salivary gland adenoid cystic carcinoma to enhance the sensitivity to chemotherapy and suppress cell proliferation and invasion; miR-101-3p was also reported to target MALAT-1 in nonsmall cell lung cancer to inhibit growth and metastasis." (PMID 32411089, 2020). "MALAT1, which is a well-known lncRNA, promotes lung cancer metastasis." (PMID 32194807, 2020). "Additionally, both Malat1 knockdown and genetic KO in a lung cancer homing model reduced homing to the lungs of lung cancer cells." (PMID 32503170, 2020). "This may be due to the regulation of MALAT1 by ALDH1A1, as MALAT1 was reported to be regulated by ALDH1A1 in lung cancer." (PMID 32244924, 2020). "Besides, lncRNAs and circRNAs are also recruited into trials, including MALAT1 in BC and lung cancer, HOTAIR in thyroid cancer." (PMID 32122355, 2020).